BRCA2 (BRCA2 DNA repair associated)
Diseases named in the same sentence as BRCA2 in open-access papers (continued):
Sharing a sentence is not in itself a finding about the gene and the disease.
breast cancer (continued). "Germline mutations of breast cancer susceptibility gene BRCA1 and BRCA2 (gBRCA1/2) are associated with elevated risk of breast cancer in young women in Asia." (PMID 36604691, 2023). "Genes have been identified to significantly increase a woman’s risk of breast cancer (e.g., BRCA1 and BRCA2, with a 70% lifetime risk of breast cancer for the women who carry mutations in these genes)." (PMID 36964875, 2023). "Data on the efficacy of tamoxifen, raloxifene, and aromatase inhibitors on breast cancer primary prevention in women carrying BRCA1 or BRCA1 and BRCA2 P/LP germline variants are scarce." (PMID 37628558, 2023). "We determined the base sequence of canine BRCA2 exon 11, which encodes the HCR and BRC repeats, in the mammary tumor samples." (PMID 36851449, 2023). "High occurrence of breast cancer due to the genetic mutation in BRCA1 and BRCA2 genes in Asian women is directly related to first-degree relatives." (PMID 37886170, 2023). "The authors identified protein-truncating variants in BRCA1, BRCA2, CHEK2, PALB2 and ATM that were significantly associated with breast cancer risk." (PMID 37662839, 2023). "On the other hand, germline mutations in BRCA2 or CDKN2A have been suggested as explanations for the link between MM and breast cancer, and CDKN2A mutations have also been proposed as a cause of the increased risk of pancreatic cancer." (PMID 37297018, 2023). "In early-onset breast cancer, concurrent germline variants of BRCA1, BRCA2, PMS2, and PALB2 were reported." (PMID 37628631, 2023). "Regarding breast cancer, most of the work looked at mutations in BRCA1 and BRCA2 with several studies reporting novel variants in these genes." (PMID 37662839, 2023). "Several studies have found that the cumulative risk of developing breast cancer by 70 years of age is 55–72% in women with BRCA1 mutations and 45–69% in women with BRCA2 mutations, whereas the cumulative risk of breast cancer in the general population is 12%." (PMID 37957733, 2023). "For women with breast cancer and a BRCA1 or BRCA2 pathogenic variant, bilateral mastectomy and oophorectomy have shown to improve survival." (PMID 36544278, 2023). "In pathogenic BRCA2 and to lesser extent BRCA1 germline mutation carriers, the presence of RAD52 p.Ser346Ter was associated with reduced risk of breast cancer." (PMID 37578974, 2023). "Individuals with mutations in the BRCA1 and BRCA2 (BRCA1/2) genes have a significantly higher risk of developing various types of cancers, especially cancers of the breast, ovary, pancreas, and prostate." (PMID 37035242, 2023). "Pathogenic variants in high‐risk breast cancer predisposition genes (BRCA1, BRCA2, and PALB2) were found in 4.5% of older women with triple‐negative breast cancer." (PMID 36544278, 2023). "Germline pathogenic mutations in breast cancer predisposition genes were identified in four patients (BRCA1, n = 2; BRCA2, n = 2)." (PMID 36879128, 2023). "Olaparib and talazoparib currently are the only PARPi approved for patients with hormone receptor-positive/HER2-negative advanced breast cancer and a BRCA1 or BRCA2 mutation detected by germline sequencing." (PMID 38414963, 2023).
breast cancer (continued). "About 25% of TNBC patients carry germline breast cancer gene types 1 and 2 (BRCA1 and BRCA2) mutations." (PMID 37719058, 2023). "Inherited mutations in the breast cancer susceptibility genes BRCA1 and BRCA2 (BRCA1/2) confer high risks of breast and ovarian cancer." (PMID 37055759, 2023). "In this prospective review of 15,104 women with breast cancer with 11-year median follow-up, CBC was seen in 5.3%, with a significant increase in women with BRCA1, BRCA2, and CHEK2 mutations (p < 0.05)." (PMID 37232811, 2023). "Young age at breast cancer (BC) diagnosis and family history of BC are strongly associated with high prevalence of pathogenic variants (PVs) in BRCA1 and BRCA2 genes." (PMID 37084156, 2023). "In SSA countries, only a few studies have explored hereditary BC through genetic analysis of breast cancer susceptibility genes such as BRCA1, BRCA2, and others." (PMID 35908255, 2023). "Four Fanconi anemia (FA) genes (BRCA1, BRCA2, PALB2 and RAD51C) are defined as breast cancer (BC) susceptibility genes." (PMID 37566130, 2023). "One of the risk factors for breast and ovarian cancers is mutations of breast cancer susceptibility genes, which were known to be BRCA1 and BRCA2—the dynamic regulators of genomic integrity." (PMID 35205313, 2022). "These variables were also associated with BRCA1 PVs carrier status except grade, whereas BRCA2 was only associated with younger age, HER2-negativity, higher grade and first degree family history of breast cancer." (PMID 35143328, 2022). "Germline pathogenic variants in the Breast Cancer Genes 1 (BRCA1) and 2 (BRCA2) are responsible for Hereditary Breast and Ovarian Cancer (HBOC) syndrome." (PMID 36230639, 2022). "Up to 1 in 10 male BRCA2 carriers develops breast cancer and displays potentially more aggressive disease relative to sporadic cases." (PMID 34320204, 2022). "The precision obtained for Intrahepatic cholangiocarcinoma was 0.88 and for Non BRCA1/BRCA2 familial breast cancer was 0.86." (PMID 36401182, 2022). "With the trend towards larger gene panels for breast cancer predisposition testing, increasing numbers of patients will be tested for BRCA1/BRCA2 and moderate risk breast CSGs." (PMID 34983940, 2022). "Another study found that breast cancers with low levels of BRCA2 mRNA expression showed a significantly higher 5-year survival rate." (PMID 35807169, 2022). "The remaining three women with PVs in BRCA2 developed ipsilateral breast cancer with one woman having ovarian cancer found incidentally during her subsequent BSO." (PMID 36091166, 2022). "Here, we assessed the associations of the newly developed 313-SNP breast cancer PRS and 147-SNP prostate cancer PRS derived using population-based data, with breast and prostate cancer risks, respectively, for male BRCA1 and BRCA2 carriers." (PMID 34320204, 2022). "The cumulative male breast cancer risk is estimated at 0.1–1.5% in BRCA1 P/LPV carriers and at 1.9–7.7% in BRCA2 P/LPV carriers." (PMID 36230512, 2022).
breast cancer (continued). "While actual breast cancer risk differs by study design and case selection, the most comprehensive updated risk estimates are 72% and 69% lifetime risk for BRCA1 and BRCA2 PSV carriers, respectively." (PMID 36349178, 2022). "Mutations in two genes known as breast cancer (BRCA) genes, BRCA1 and BRCA2, are linked with 5 to 10% of all breast cancers." (PMID 36421343, 2022). "The objective of this study is to search for mutations in the BRCA1 (c.5177_5180delGAAA and c.4986+6T>C) and BRCA2 genes (c.6445_6446delAT) in a population of women diagnosed with breast cancer." (PMID 35950060, 2022). "Some studies have reported that breast cancer patients who are germline carriers of pathogenic variants in DNA repair genes such as BRCA1 and BRCA2 are at higher risk of FN." (PMID 35681694, 2022). "In the mutation driver module for breast cancer, both BRCA1 and BRCA2 are exactly connected to PARP1." (PMID 36266635, 2022). "For example, a study on breast cancer patient’s genomes showed a widespread loss of miR-3613-3p DNA fragment, located near the tumor suppressor genes RB1 and BRCA2 (13q13.1)." (PMID 35200555, 2022). "We studied matched primary and recurrent breast cancers from 13 subjects, nine BRCA1 and four BRCA2 pathogenic variant carriers." (PMID 36344544, 2022). "Breast cancer unaffected and affected women with a pathogenic variant in the BRCA1 or BRCA2 gene were psychologically evaluated immediately before (T0), 6 to 8 weeks (T1) and 6 to 8 months (T2) after the disclosure of their genetic test results." (PMID 36536421, 2022). "Somatic homozygous deletion, labeled as deep deletion, were observed in BRCA2 in a single breast cancer patient and in pancreatic cancer (RAD51B (n = 2), RAD51C (n = 2) and XRCC2 (n = 1))." (PMID 35783256, 2022). "Regarding men with mutations in the BRCA2 gene, as well as BRCA1 mutations (although with lower associated risks), they also have a higher risk of developing cancer, namely breast cancer and prostate cancer." (PMID 35805026, 2022). "Disruption of the interaction between RAD51 and BRCA2 leads to genomic instability and the development of mammary tumors." (PMID 36548864, 2022). "Four recurrent variants were discovered among unrelated African-descended breast cancer patients: BRCA1:c.3331_3334delCAAG, BRCA1:c.211A>G, BRCA2:c.1389_1390delAG, and PALB2:c.1671_1674delTATT." (PMID 35353237, 2022). "The aim of this study was therefore, to determine the prevalence of (rs80357867, rs80358086) of the BRCA1 gene and (rs80359592) of the BRCA2 gene, with a view to contributing to breast cancer prevention in Burkina Faso." (PMID 35950060, 2022). "According to statistics, 20% to 40% of hereditary breast cancers can be attributed to harmful mutations in BReast CAncer gene 1 (BRCA1) and BReast CAncer gene 2 (BRCA2)." (PMID 35402620, 2022). "Estimated lifetime risk for developing breast cancer in individuals harboring these germline variants is upwards of 72% and 69% for BRCA1 and BRCA2 respectively." (PMID 35685436, 2022). "Here, we have conducted the largest and most comprehensive genome-wide association study of CNVs and breast cancer risk for BRCA1 and BRCA2 pathogenic variant carriers." (PMID 36203093, 2022). "Several genetic alterations are strongly associated with an elevated risk of breast cancer, of which BRCA1 (chromosome 17) and BRCA2 (chromosome 13) are the two important genes with great penetrance." (PMID 36110451, 2022). "PALB2 is characterized as an important predisposing to breast cancer gene after BRCA1 and BRCA2, despite the fact that it is classified as a gene with moderate penetrance." (PMID 36230696, 2022).
breast cancer (continued). "For the breast cancer with BRCA1 and BRCA2 mutations, there is a strong association with an increased risk for a second breast or ovarian cancer." (PMID 35281878, 2022). "The estimated average cumulative risk of breast cancer to age 70 years was estimated to be 52% (95% CI, 26–69%) for BRCA1 mutation carriers and 47% (95% CI, 29–60%) for BRCA2 mutation carriers." (PMID 35409110, 2022). "Breast cancer susceptibility gene one (BRCA1) and two (BRCA2), are well established tumor suppressor genes that play a pivotal role in promoting HR in response to DNA damage." (PMID 36497436, 2022). "PVs of ATM and CHEK2 confers greater than 30% lifetime risk for breast cancer, but lower than that of BRCA1 and BRCA2, thus are regarded as moderate-high risk." (PMID 35323371, 2022). "Breast cancer-associated genes 1 and 2 (BRCA1 and BRCA2) are tumor suppressor genes encoding a large protein that is involved in many essential biological processes." (PMID 35573021, 2022). "In South-Eastern Norway, genetic testing for BRCA1 and BRCA2 is offered to breast cancer patients by their treating surgeon or oncologist." (PMID 35123550, 2022). "The predicted proportion of breast cancer cases possessing pathogenic germline missense variants in these genes is approximately 0.6%, 0.3%, 0.2%, and 1.3% for ATM, BRCA1, BRCA2, and CHEK2, respectively." (PMID 35585550, 2022). "Absence of adjuvant chemotherapy was the most powerful factor that was linked to a dramatic decline in survival for patients with breast cancer with BRCA1 and BRCA2 mutation." (PMID 36580360, 2022). "Breast cancer mean onset was 4.6 years earlier in BRCA1 carriers compared to BRCA2 (p = 0.07, a trend) and ovarian cancer onset almost 11 years earlier in BRCA1 families (p < 0.05)." (PMID 35469032, 2022). "The cumulative risk of developing breast cancer at the age of 70 for carriers of BRCA mutations is 65% for BRCA1 and 45% for BRCA2." (PMID 35744786, 2022). "PRSBC and PRSER+ were associated with larger odds ratio estimates than PRSER- in predicting breast cancer risk, consistent with the fact that most breast cancers in men are ER positive, including those harboring BRCA1 and BRCA2 pathogenic variants." (PMID 34320204, 2022). "BRCA2 germline PVs ranks first (3.5%) among all germline PVs reported by an investigation conducted in 8085 unselected breast cancer patients in China." (PMID 36518309, 2022). "For our exemplar clinical scenario, we applied this pathway to BRCA-testing (BRCA1/BRCA2/PALB2 gene testing) in unselected mainstream patients with breast cancer." (PMID 35868849, 2022). "It has been established that breast cancer development has genetic undertones with breast cancer susceptibility genes 1 and 2 (BRCA1 and BRCA2) as the most famous." (PMID 36942145, 2022). "Protein truncating variants in ATM, BRCA1, BRCA2, CHEK2, and PALB2 are associated with increased breast cancer risk, but risks associated with missense variants in these genes are uncertain." (PMID 35585550, 2022). "A previous study showed that the probability of breast cancer in BRCA1 mutation carriers is 57–65%, while the probability of breast cancer in BRCA2 mutation carriers is 45–49%." (PMID 35409110, 2022). "The protective role of RRBSO in patients with luminal breast cancer increased with their age at diagnosis, stage of the disease, and was impacted by the type of pathogenic variant (BRCA1 or BRCA2)." (PMID 36580360, 2022).
breast cancer (continued). "In the past, genetic testing was based only on the high-penetrance genes such as BRCA1 and BRCA2, which account for around 12 to 15% of ovarian cancers (OC) and 3 to 5% of breast cancers (BC) in most populations worldwide." (PMID 35886069, 2022). "Key to this process is the breast cancer susceptibility genes BRCA1 and BRCA2 as well as the accessory RAD52 gene." (PMID 36530474, 2022). "In the Chinese cancer patients, a study showed that the prevalence rate was 5.53% for BRCA1/2 (43.7% in BRCA1 and 56.3% in BRCA2) in unselected breast cancer patients." (PMID 36439508, 2022). "Pathogenic variants in the BRCA 1/2 genes represent a significant risk factor for cancer development, with a lifetime cumulative risk up to 72–69% for breast cancer and 44–17% for ovarian cancer for BRCA1 and BRCA2 pathogenic variant carriers, respectively." (PMID 35884518, 2022). "In general, the prevalence and spectrum of the BRCA1 and BRCA2 genes in the Hakka patients with breast cancer and ovarian cancer from southern China are different from those in other ethnic groups." (PMID 35918668, 2022). "Although BRCA1 and BRCA2 have been studied extensively, other genes are also involved in the occurrence of breast cancer." (PMID 35785170, 2022). "In patients with breast cancer with the BRCA1 and BRCA2 pathogenic variants with luminal breast cancer in stage II, RRBM + RRBSO had a very modest impact on survival compared with surveillance." (PMID 36580360, 2022). "Previous studies suggest the magnitude of the breast cancer PRS associations is attenuated in female BRCA1 and BRCA2 carriers compared with associations seen in the general population." (PMID 34320204, 2022). "Up to 10% of breast cancer is due to genetic predisposition, with inherited mutations in breast cancer gene 1 (BRCA1) or BRCA2 (herein referred to as BRCA1/2) accounting for most cases." (PMID 35025760, 2022). "These hereditary breast cancers, a large part about 80-90% cases, are related to germ line mutations within the BRCA1, BRCA2, and MDR1 gene." (PMID 35837379, 2022). "Among 91 patients with HER-2-negative advanced or relapsed breast cancer, including 2 men and 89 women, 8 were diagnosed with pathogenic or likely pathogenic variants: BRCA1 (n = 4) and BRCA2 (n = 4)." (PMID 35627717, 2022). "In conclusion, our study provides evidence that CNVs contribute to the variability in breast cancer risk among BRCA1 and BRCA2 pathogenic variant carriers." (PMID 36203093, 2022). "Linkage studies in families with breast cancer at an early age suggest that mutation in BRCA1 and BRCA2 is linked to breast cancer predisposition." (PMID 35163783, 2022). "Of the breast cancer susceptibility genes which have been identified nowadays, BRCA1 and BRCA2 are the most fundamental “high-risk” genes with several cases of breast and ovarian cancer accounting for most of the families." (PMID 35837379, 2022).